NUTM2D (NUT family member 2D)
Synonyms: FAM22D
Tractability: No criterion of Open Targets' tractability assessment is met for any kind of drug.
Gene: Protein-coding gene on chromosome 10 (87,357,720 to 87,370,695, forward strand). Ensembl gene ENSG00000214562.
Subcellular location (Human Protein Atlas): Nuclear bodies
Genetic constraint (gnomAD): Loss-of-function variants: 1 observed, 10.22 expected, observed/expected ratio (o/e) 0.0979, 90% interval 0.034 to 0.46. The synonymous counts are far from expectation, so gnomAD's model fits this gene poorly and the ratio says little. Missense variants: 13 observed, 139.39 expected, observed/expected ratio (o/e) 0.0933, 90% interval 0.06 to 0.15. Synonymous variants: 9 observed, 50.06 expected, observed/expected ratio (o/e) 0.18, 90% interval 0.11 to 0.31.
Homologues: Orthologues: macaque NUTM2A (83% identical), rat Nutm2 (37% identical), mouse Nutm2 (35% identical). Paralogues in human: NUTM2A (98% identical), NUTM2B (97% identical), NUTM2E (97% identical), NUTM2F (79% identical), NUTM2G (77% identical), NUTM1 (44% identical).
Diseases named in the same sentence as NUTM2D in open-access papers:
NUTM2D is named in the same sentence as 2 diseases in open-access papers, as found by Europe PMC text mining. Sharing a sentence is not in itself a finding about the gene and the disease.
NUTM2D shares sentences with these, for which no sentence is quoted: brain tumor (1 paper); tumor (1).